RHOA (ras homolog family member A)
Diseases named in the same sentence as RHOA in open-access papers (continued):
Sharing a sentence is not in itself a finding about the gene and the disease.
cancer (continued). "RhoA has been described as an important regulator of cell cycle progression of some human cancers and cancer-associated mutations in Rho family regulators have been characterized." (PMID 38067102, 2023). "The upregulation of RhoA is associated with several epithelial human cancer tissues including breast, testicular, liver, ovarian and gastric carcinoma." (PMID 36854376, 2023). "Across a range of cancer types, RHOA overexpression is associated with oncogenesis, in patients and cell line models, as well as advanced disease, further highlighting its role in progression of cancer." (PMID 35119068, 2022). "RhoA protein has been implicated in cancer progression contributing to cell proliferation, survival, and migration." (PMID 35273919, 2022). "Increasing evidence has associated elevated RhoA signaling with human cancer metastasis and progression, through increased RhoA expression, activating mutation or increased expression of GEFs, or from deletion or decreased expression of GAPs." (PMID 36555100, 2022). "Abnormal expression of RhoA has been implicated in various diseases, including cancers, developmental disorders and bacterial infections." (PMID 36555100, 2022). "Genomic analysis showed that mutations in RHOA in cancer cells (which promote tumor progression) activate the PI3K-AKT-mTOR signaling pathway, increasing the production of free fatty acids that are consumed more efficiently by Treg cells than Teff cells." (PMID 35444235, 2022). "The most prevalent cancer-associated RhoA mutation G17V is also an activating mutation, which impairs RhoA’s GTP hydrolysis activity." (PMID 36555100, 2022). "RhoA mutations or abnormal expression have been reported to be closely associated with the development of malignant tumors." (PMID 35076580, 2021). "The Rho family member RhoA, one of the major players in amoeboid cell migration, has been previously linked to EV shedding in cancer cells." (PMID 34532864, 2021). "Up until now, there are no RhoA mutations corresponding with cardiac diseases known yet, but there is good evidence for direct correlations between mutations of the RhoA-gene as well as known mediators of RhoA signaling pathways and cancer." (PMID 34359851, 2021). "Due to the critical functions of RHOA in cell proliferation, migration and apoptosis, it is expected that RHOA dysfunction is also associated with cancer." (PMID 33406731, 2021). "On the other hand, CXCR4 promote cancer progression in APCMin mice by causing cytoskeleton alterations and recruitment of immune cells, in a RHOA dependent mechanism." (PMID 33406731, 2021). "The overexpression of RhoA and Rac1, members of the Rho GTPases, have been linked with carcinogenesis and the progression of different types of cancer." (PMID 32731493, 2020). "The activation of RhoA has been associated with cancer cell proliferation, progression, and metastasis via the RhoA-Rho-associated protein kinase (ROCK) signaling pathway." (PMID 32377503, 2020). "Recent studies have identified activating mutations in Rho GTPases, such as RhoA, Rac1, and Cdc42, in various human cancers." (PMID 32392742, 2020). "There are many reports demonstrating that overexpression of RhoA associated with various cancers' progression such as testicular cancer, breast cancer, colon, lung cancers, and head and neck squamous cell carcinoma." (PMID 32802134, 2020). "Collectively, these findings revealed that in response to CXCL12/CXCR4 activation, miR-133a-3p was repressed and implicated with cancer cell motility by upregulating RhoA through direct binding to RhoA 3’UTR." (PMID 30678736, 2019). "Overall, the majority of RHOA functions, in invasion, primarily encompass cancer hallmark #2 (resistance to cell death)." (PMID 31156701, 2019). "Our own previous study using a RHOA-mutated cancer cell line supported these reports by revealing that, compared with subcutaneous models, orthotopic models exhibited abundant stroma and an invasive character." (PMID 31485674, 2019).
cancer (continued). "The members of Rho GTPases, Rac1, Cdc42, and RhoA, have been considered as classical cytoskeleton regulators associated with cancer cell migratory phenotype." (PMID 31019460, 2019). "It was reported that RhoA is implicated in cancer metastasis and its gene transcription is regulated by c-Myc, therefore, we detected the expression of c-Myc and RhoA after exposure to SNS-032." (PMID 31526394, 2019). "Accumulated evidence has demonstrated that RhoA was closely associated with cancer in relation to venous invasion, microscopic satellite lesions, advanced pTNM stage, progression, cell differentiation and disease-free survival rates." (PMID 31339860, 2019). "Early studies within which mutations in RhoA were designed based on cancer-associated mutations in Ras supported an oncogene role for RhoA." (PMID 31705019, 2019). "The cancer hallmark term, “sustainment of proliferative signaling” (hallmark #3 above), has yet to be clearly linked to GC, with specific regard to RHOA." (PMID 31156701, 2019). "Recent advances in whole-genome sequencing have identified hitherto undiscovered mutations in cancers and identified recurrent loss-of-function and gain-of-dominant-negative function mutations in RhoA in lymphoma, leukemia and several solid tumors." (PMID 31705019, 2019). "For instance, various cancer tissues and cell lines show elevated levels of Ephexin2, which results in the increased activity of RhoA causing higher cancer proliferation, migration, and invasion." (PMID 30682817, 2019). "CD44(+) GC CSC cell numbers were decreased by cisplatin combined with RHOA signaling inhibitors; A cancer hallmark term, resisting cell death (cancer stem-like cells, CSCs) associated." (PMID 31156701, 2019). "To identify which mutation sites contribute to cancer cell survival, we selected RHOA-mutated cell lines from public databases and chose 12 cell lines." (PMID 29796182, 2018). "Activation or over-expression of FAK and RhoA in cancer cells has been found to be associated with cancer aggressiveness and metastasis as well as poor patient survival." (PMID 29491429, 2018). "In our previous work, we observed that a knockdown of RHOA in RHOA-mutated cancer cell lines represses cell survival significantly." (PMID 29796182, 2018). "In this study, we revealed that CLG fusions and RHOA mutations share a functional relationship; namely, in promoting cancer cell survival and migration." (PMID 29796182, 2018). "The identification of cancer-associated somatic mutations in Rac1 and RhoA, and more recently also in Cdc42, has demonstrated that the Rho GTPases appear to have more active roles in cancer progression than originally thought." (PMID 30544828, 2018). "Second, it is noteworthy that RhoA is implicated in both lamellipodium-driven and bleb-driven migration in 3D environments, contributing to cancer cell motility." (PMID 30148884, 2018). "In this study, we revealed that RHOA mutations promoted cancer cell survival and migration activity by inactivating ROCK." (PMID 29796182, 2018). "This mutual exclusivity was confirmed in our study (data not shown) and provides strong genetic evidence that both the CLDN18-ARHGAP fusion and RHOA mutations are cancer drivers in the same pathway." (PMID 30034621, 2018). "suggest that in cancer, doxorubicin‐triggered RhoA activation is associated with phospho‐cofilin dephosphorylation due to PDXP activation 48, and LPS was reported to dephosphorylate cofilin via PDXP induction." (PMID 29363851, 2018). "Crucially, ZA administration reverts cancer associated fibroblasts (CAFs) activation by targeting the mevalonate pathway and RhoA geranyl-geranylation, thereby impairing smooth muscle actin-α fibers organization, a prerequisite of fibroblast activation." (PMID 27223431, 2017). "Cytosolic CTNND1 drives E-cadherin-deficient cancer cell migration, invasion and metastasis through activation of Rho-family GTPases Rac1 and Cdc42 and inhibition of RhoA activity." (PMID 29228664, 2017).
cancer (continued). "ROCK1 mediates the Smad-independent, TGFβ/RhoA signaling axis, and has also been shown to be an important mediator of cancer-associated fibroblast (CAF) activation and deposition of extracellular matrix (ECM) proteins in solid tumors." (PMID 28841710, 2017). "Y-27632, another RhoA pathway inhibitor, was shown to cause cellular apoptosis in some cancer cell lines." (PMID 27145964, 2016). "At the cellular level, the loss of SCN4B/β4 in cancer cells further stimulates their invasiveness by favouring amoeboid migration, supported by the overactivation of the RhoA pathway, yet keeping the ECM-degradative activity intact." (PMID 27917859, 2016). "The LARG (leukemia-associated Rho GEF) protein mediates activation of RhoA and signals for bleb-associated cancer evasion." (PMID 27304967, 2016). "RHOA encodes the small GTPase RhoA and regulates cancer cell contractility, cellular motility and metastasis of GC and other malignant tumors." (PMID 27756879, 2016). "These mutants are analogous to the Ras-V12 (constitutively active) and Ras-N17 (dominant negative) mutants found in ~25% of all human cancers, in marked contrast to RhoA mutations, which are rarely found." (PMID 26649141, 2016). "Recent studies have discovered recurrent RHOA mutations in diffuse-type gastric cancers.These reports show mutant RhoA is an important cancer driver and is a potential therapeutic target." (PMID 25823974, 2016). "The loss of SCN4B/β4 enhances cancer cell migration and metastases formation through a RhoA-dependent signalling pathway, independently of pore-forming NaV subunits." (PMID 27917859, 2016). "Histologically, although all of the tumors were predominantly or exclusively composed of poorly cohesive carcinoma, limited tubular differentiation was also observed in 73 % of the RHOA-mutated tumors." (PMID 25823974, 2016). "Cells respond to stiff extracellular matrices via Rho-activated actin stress fibers and overactive RhoA signaling is linked to cancer [see 32 for review]." (PMID 25211221, 2014). "Here, loss of RhoGAPs, such as DLC1, is associated with cancer, which suggest that RhoA signaling affects cell fate." (PMID 25211221, 2014). "RhoC has been implicated in the enhancement of cancer cell migration and invasion, with actions which are distinct from RhoA (84% homology), and are possibly attributed to the divergent C-terminus domain." (PMID 24312560, 2013). "RhoA, a member of the Rho GTPase family, has been implicated to be involved in the development and/or progression of numerous cancers." (PMID 24191200, 2013). "The hubs, (Rac1, Cdc42, RhoA, and HRas) identified in the network are widely studied proteins due to their association with human cancers and core cellular processes." (PMID 23028658, 2012). "Note that integrin-β1 downstream signaling players RhoA is known to regulate the actin stress fiber-coordinated fibronectin matrix assembly, which is associated with cancer colonization and metastasis in the lungs." (PMID 22279574, 2012). "RhoA has been implicated in virtually all stages of cancer progression and metastasis, whereas RhoC is restricted to metastasis." (PMID 22016776, 2011). "RhoA has been implicated in virtually all stages of cancer progression: for example, in vitro, constitutively active RhoA can stimulate transformation." (PMID 20822528, 2010). "Such modifiers could help to identify pathways uniquely engaged by each class of mutation and ultimately inform therapeutic strategies for RHOA-driven cancers." (PMID 41002403, 2025). "Interestingly, COSMIC (Catalogue of Somatic Mutations in Cancer) analysis revealed that K118 and K162 are two cancer-associated and naturally occurring missense mutation hotspots in RHOA." (PMID 41291745, 2025). "Altered cellular forces, AJs, and RhoA signaling have all been implicated in cancer." (PMID 38970683, 2024). "Thus, CLDN18-ARHGAP fusion is possible a factor for RHOA mutation to maintain cancer cell survival and promoted cell migration." (PMID 36969060, 2023).
cancer (continued). "We therefore probed further into the fourth node in this high-confidence edge network: ANLN/Anillin, a cytoskeletal scaffold protein that links RhoA, actin, and myosin during cytokinesis, with additional emerging nuclear roles in cancer-associated gene transcription." (PMID 36549590, 2023). "HGF-related actin rearrangement, which is linked to cancer cell morphogenesis and metastasis, is primarily regulated by small GTPase activity, especially RhoA, Rac1, and Cdc42; however, various types of cancer cells use distinct signaling pathways in response to HGF to activate small GTPase." (PMID 35630066, 2022). "The RhoA/ROCK pathway has been implicated in dynamic crosstalk regulation between cancer cells and their microenvironment, which may be used to inhibit cancer metastatic processes." (PMID 35277915, 2022). "Notably, restoration of RhoA expression in Skp2 deficiency cancer cells fully rescues the defects in cancer cell migration and invasion." (PMID 36180910, 2022). "However, initial studies on RhoA were based on cancer-associated mutations in Ras that supported an oncogene role for RhoA." (PMID 35076580, 2021). "Similarly, the various mutations identified in RHOA in cancer cells are likely to perturb its interactome." (PMID 32526908, 2020). "The cancer hallmark term, “resistance to cell death” (#2 above), also highly associated with RHOA." (PMID 31156701, 2019). "Recently, we revealed that RHOA mutations contribute to cancer cell survival and cell migration through their dominant negative effect on the Rho-associated kinase (ROCK) pathway, but little is understood of how these functions are related to the clinicopathological features of DGC." (PMID 31485674, 2019). "It was previously reported that RhoA GTPase is implicated in cancer metastasis." (PMID 31526394, 2019). "Ras homolog family member A (RHOA) mutations are driver genes in diffuse-type gastric cancers (DGCs), and we previously revealed that RHOA mutations contribute to cancer cell survival and cell migration through their dominant negative effect on Rho-associated kinase (ROCK) signaling in vitro." (PMID 31485674, 2019). "Overexpression of the lncRNA PCGEM1 (prostate cancer gene expression marker 1) promotes cancer growth by upregulating protein expression of RhoA and its downstream factors YAP (Yes-associated protein), MMP2 (matrix metalloproteinase 2), Bcl-xL and P70S6K in ovarian cancer." (PMID 31248165, 2019). "For RHOA, both gain- and loss-of-function mutations have been detected in human cancers." (PMID 31248017, 2019). "Considering the crucial roles of RhoA in the regulation of cell morphology, motility, and cell-cell and cell-matrix adhesion, we can easily deduce that RhoA is associated with carcinoma metastasis, which is one of the leading causes of death in patients with solid tumors." (PMID 31339860, 2019). "Secondly, ROCK activation induced cell death in RHOA mutated cancer cells." (PMID 29796182, 2018). "Here we examined how RHOA mutations affect cancer cell survival and cell motility." (PMID 29796182, 2018). "RhoA has been implicated in virtually all stages of cancer progression." (PMID 26209534, 2015). "Overexpression of RhoA and Rho GTPases are linked to cancer and the stability of RhoA transcripts in cancer cells has been shown to be a result of altered polyadenylation signals, further suggesting why it would be biologically important to have more than one RhoGAP regulating Rho GTPases." (PMID 25211221, 2014). "RhoA has been shown to be an important factor associated with various human cancers." (PMID 22235332, 2012). "RhoA and RhoC proteins have implicated them as important factors in promoting the uncontrolled proliferation and invasive and metastatic properties of cancer cells, however, it is poorly understood how they are activated in cancer cells." (PMID 20828398, 2010).
cancer (continued). "In both cases, inhibition of RhoA modulation led to reduced cell motility, strengthening the notion that the regulation of RhoA activity is causally involved in the pro-migratory phenotype observed in podoplanin-expressing cancer cells." (PMID 17179989, 2007). "While its silencing leads to a loss of stress-fiber-associated RhoA, suggesting it acts as a scaffold linking RhoA to regulate myosin phosphatase at the stress fiber, its phosphorylation at S891 has been found in global phosphoproteomic studies in the context of mitosis and cancer." (PMID 37569500, 2023). "In addition, RhoA/ROCK has been linked with the progression of different cancers." (PMID 33552977, 2020). "Therefore, targeting RhoA/ROCK signaling-associated miRNAs could be useful strategy for inhibiting migration of cancer cells in treatment of cancer metastasis." (PMID 30678736, 2019). "Indeed, mutated RHOA proteins could act as tumor suppressors in human cancers, as well as another member of the RHOA subfamily, RHOB, that is frequently deleted in human lung cancer." (PMID 31248017, 2019). "Since the features of this xenograft model allow insights into the biology in human clinical cancer, these results will accelerate the understanding of how RHOA mutations contribute to the disease biology of DGC and may promote the development of future therapeutic strategies." (PMID 31485674, 2019). "Ras homolog family member A (RhoA) is a therapeutic hotspot in many cancers but remains undruggable." (PMID 41984592, 2026). "RAS homolog family member A (RHOA), a key regulator of cell motility, is frequently upregulated in response to hypoxia across cancers." (PMID 40600795, 2025). "Previous studies have demonstrated that RSK2 interacts with small GTPases, such as RhoA, to promote cytoskeletal reorganisation, thereby enhancing the migratory capacity of cancer cells." (PMID 40762406, 2025). "RhoA senses liver stiffening from cancer or fibrosis, triggers PI3K–AKT–p300 signaling, and drives HSC‐to‐myofibroblast conversion." (PMID 41377763, 2025). "Therapeutically, combined targeting of lactate metabolism and RHOA signaling represents a promising strategy for lactylation-driven cancers, bridging metabolic and genetic approaches in precision oncology." (PMID 41291745, 2025). "The relative expression level of RhoA is significantly elevated in the LS513 cancer cell line following mechanical strain, in contrast to the FHC non‐cancer cell line, which does not exhibit any notable increase after stretching." (PMID 39887960, 2025). "The subsequent assessment of RhoA and Rac1 expression across the cancer cell population revealed that these biomarkers are widely present, with a significant portion of cells expressing one or both proteins." (PMID 39887960, 2025). "When LARG is deleted in cancer cells, RhoA activation is significantly reduced, and invasion and migration are impeded." (PMID 41338458, 2025). "RhoA and Ezrin are recognized proto-oncogenes, frequently overexpressed in various cancer types, which further underscored their potential importance in the context of miR-183 regulation." (PMID 40630207, 2025). "This work contributes to a deeper understanding of how cellular adaptations to hypoxia shape the behavior of cancer cells and shows that RHOA-mediated mitochondrial regulation has potential as a future therapeutic strategy for treatment of advanced GC." (PMID 40600795, 2025). "This differential response highlights the unique mechanotransduction pathways activated in cancer cells, suggesting that RhoA plays a critical role in how cancer cells adapt to mechanical stress." (PMID 39887960, 2025). "An incresaing number of studies have gradually highlighted the pivotal role of RhoA and Rac1 in cancer development and progression." (PMID 39887960, 2025). "Although the role of RhoA and Rac1 in cancer progression is well‐established, it is interesting to further investigate how mechanical strain influences their expression and activity in CRC." (PMID 39887960, 2025).